ASS1P2 (argininosuccinate synthetase 1 pseudogene 2)
Synonyms: ASSP2
Gene: Processed pseudogene on chromosome 2 (38,810,432 to 38,811,654, reverse strand). Ensembl gene ENSG00000223922.
Diseases named in the same sentence as ASS1P2 in open-access papers:
ASS1P2 is named in the same sentence as 3 diseases in open-access papers, as found by Europe PMC text mining. Sharing a sentence is not in itself a finding about the gene and the disease.
ASS1P2 shares sentences with these, for which no sentence is quoted: cancer (1 paper); pancreatic cancer (1); tumor (1).